BAP1 (BRCA1 associated deubiquitinase 1)
Diseases named in the same sentence as BAP1 in open-access papers (continued):
Sharing a sentence is not in itself a finding about the gene and the disease.
tumor (continued). "BRCA1‐associated protein 1 (BAP1) negativity was seen in the nucleus of neoplastic cells, reflecting the loss of BAP1 tumor suppressor genes." (PMID 36808895, 2023). "Larger tumours are more likely to harbour many of the risk factors associated with worse outcomes including BAP1 mutations, vasculogenic mimicry and M3." (PMID 35801361, 2023). "One of the most striking examples from this analysis was CES3, which showed both reduced gene expression and reduced accessibilities of associated enhancer peak in BAP1-mutant tumor cells." (PMID 36973268, 2023). "VHL mutations, for example, are associated with defined tumor margins, nodular tumor enhancement, and intratumoral vascularization, while a greater vein invasion is significantly associated with BAP1 mutations." (PMID 36902045, 2023). "Nonetheless, the mechanisms underlying the tumor suppressor function of BAP1 have only begun to be uncovered." (PMID 37009801, 2023). "Although BAP1 was originally identified as a protein associated with the BRCA1 tumor suppressor, the significance of the BAP1 and BRCA1 interaction has thus far remained unclear." (PMID 37009801, 2023). "BAP1 mutations are early events in tumorigenesis, likely occurring when the tumor still consists of a few malignant cells." (PMID 37958591, 2023). "Among them, the presence of TERT promoter (TERTp) mutations, homozygous deletion of CDKN2A/B, BAP1 loss of nuclear expression have all been associated with increased tumor aggressiveness." (PMID 37010677, 2023). "Other germline cases described have been in individuals with a personal or family history of BAP1-associated tumours." (PMID 37607989, 2023). "Tumours with BAP1 mutations are detected in up to half of all UM and often lead to metastasis within 5 years." (PMID 36662495, 2023). "The majority of the patients with a BIM demonstrating loss of BAP1 on IHC and a BAP1 GPV had a personal or family history of any other BAP1 associated tumour (10/12 cases)." (PMID 37607989, 2023). "As for many other cancer predisposition genes, existing BAP1 testing criteria have generally been based on personal history of BAP1-TPDS associated tumours or a personal and family history of BAP1-TPDS associated tumours." (PMID 37607989, 2023). "Chromosome 3 and 8 abnormalities and germ-line BAP1 mutations correlate with traditional factors of poor prognosis, such as larger tumour diameters." (PMID 36805408, 2023). "Of note, in UM patients, the presence of somatic BAP-1 mutations in tumour cells increases the risk of metastasis and worsens prognosis." (PMID 38087265, 2023). "More recent guidelines have suggested the addition of young age of onset of a BAP1-associated tumour." (PMID 37607989, 2023). "Loss of expression of BAP-1 in a majority of tumor cell nuclei (low nBAP-1) is a strong marker for poor patient prognosis in UM." (PMID 36973672, 2023). "The overall lifetime risk for BAP1 carriers to develop at least one BAP1-associated tumour is up to 85%, although due to ascertainment bias, current estimates of risk are likely to be overestimated." (PMID 37607989, 2023). "A moderate separation based on metabolite patterns is seen between the three molecular subclasses, which is more profound in the PLS-DA comparing only the metabolite patterns of patients harboring a BAP1 or EIF1AX-mutated tumor." (PMID 36982149, 2023). "Other driving mutations, including SETD2, PBRM1 and BAP1, lead to genomic instability and promote tumor cell metastasis through the disorder of various metabolic and immune response pathways." (PMID 36966163, 2023). "As described in the prevalence section, the detection rate for a germline BAP1 pathogenic variant is higher where there is a personal or family history of other BAP1-associated tumours and lower for isolated cases." (PMID 37607989, 2023).
tumor (continued). "Of these, four cases had a family history of a BAP1-associated tumour, one had personal history of another malignancy and one was an isolated case, again demonstrating a higher detection rate in the presence of relevant personal or family history." (PMID 37607989, 2023). "BAP1 GPV are now being identified not only in individuals with BAP1-associated tumours, but also as incidental findings as part of larger gene panels." (PMID 37607989, 2023). "These roles of BAP1 likely account at least in part for its tumor suppressor function in human cancers associated with BAP1 cancer syndrome." (PMID 37009801, 2023). "Regarding tumor mutation, we discovered that BAP1 was more frequently mutated in the Cluster1 subtype, which was consistent with prior evidence suggesting BAP1 mutations enhance the possibility of UM patients developing metastases." (PMID 37268878, 2023). "Harbour and colleagues reported that alterations in BAP1, which is encoded by a gene on chromosome 3p21 and is essential for neoplasm inhibition, were related to higher distant metastases risk." (PMID 36662495, 2023). "The BRCA-1 associated protein (BAP1) is a deubiquitinating enzyme with a role in tumor suppression, regulating cell proliferation and growth." (PMID 37010677, 2023). "BAP1 is a tumor suppressor gene encoding BRCA1-associated protein-1, which plays a role in DNA repair and cell cycle regulation." (PMID 37761023, 2023). "BAP1 is a tumor suppressor gene that encodes a nuclear deubiquitinase involved in cell growth and cancer pathogenesis, mapping on chromosome 3 (3p21.1)." (PMID 36765733, 2023). "Tumor size is strongly associated with virtually all other prognostic factors in UM, including ciliary body involvement, BAP1 mutation, gene expression class 2, monosomy 3, tumor cell type, and patient age." (PMID 36973672, 2023). "Mutations in PBRM1 and BAP1 are also critical driver events of ccRCC tumor development and are known to be prognostic for outcomes in RCC." (PMID 37173966, 2023). "These authors found that the xc− antiporter is a target of BRCA1-associated protein 1 (BAP1) and that BAP1 promotes ferroptosis through repressing xc− antiporter expression, resulting in tumor suppression." (PMID 37461634, 2023). "BRCA1-associated protein-1 (BAP1), also known as UCHL2 can regulate various cellular processes including cell cycle, cell differentiation, transcription, DNA damage response, and resistance to tumor radiotherapy." (PMID 36613989, 2022). "As BAP1 is frequently mutated in human cancers, BAP1 mutation contributes to tumor development by abrogating its ability to suppress the SLC7A11 expression and induce ferroptosis." (PMID 36552652, 2022). "Due to limited DNA concentration, four SCNA-positive AH samples (UM_005, 007, 012, and 013) were further evaluated for the presence of tumor variants in the BAP1 and GNAQ genes." (PMID 35682905, 2022). "Other targeted therapies have been slow to emerge for MPM, which lacks common oncogenic drivers, and instead is characterised by loss-of-function mutations in tumour suppressors, most commonly BAP1, P16 and NF2." (PMID 36497318, 2022). "The tumour suppressor BRCA1‐associated protein‐1 (BAP1) is a nuclear deubiquitylase encoded on chromosome 3p." (PMID 35474453, 2022). "Particularly, the authors found a better overall survival for patients with BAP1 mutations, protein expression loss, or at least one of these alterations independently of tumour histological subtype, age, and sex." (PMID 35223506, 2022). "Recently, however, we estimated that the BAP1 mutation occurs when the primary tumor has a size of only a few malignant cells to 6 mm3." (PMID 34775516, 2022).
tumor (continued). "Loss-of-function BAP1 mutations are associated with higher tumor grade and poorer prognosis in ccRCC." (PMID 35941663, 2022). "For instance, ATG5 is considered a contributor for inducing ferroptosis, and its high expression promotes tumor metastasis; BAP1 encodes a nuclear deubiquitinating enzyme, which plays an important role in ferroptosis and tumor suppression." (PMID 35042463, 2022). "Most of these are truncating variants with somatic inactivation of the second allele leading to BAP1 deficiency, evident as loss of immunohistochemical staining for BAP1 protein in tumor cell nuclei." (PMID 35381901, 2022). "They include tumor size, chromosome 3 monosomy, loss of BRCA1 associated protein-1 (BAP1), eukaryotic translation initiation factor 1 (EIFAX) and splicing factor 3 subunit 1 (SF3B1) mutations (increasing the risk of metastases in disomy 3 tumors)." (PMID 36619870, 2022). "The BRCA1 (BReast CAncer gene 1)-associated protein (BAP1) gene encodes a 729-residue-long tumor suppressor protein that functions via multiple incompletely understood pathways." (PMID 36292588, 2022). "Analysis of tumour biopsies (n = 63) showed that 61 (97%) had likely loss of one copy of BAP1, 23 (37%) had mutations in the gene encoding GNAQ, 26 (41%) in GNA11, three (5%) in CYSLTR2, one (2%) in PLCB4 and 11 (17%) in SF3B1." (PMID 36229663, 2022). "We found loss of BAP1 significantly reduced tumor progression and cell viability both in vitro and in vivo using two distinct BAP1 gRNAs." (PMID 35194152, 2022). "Somatic BAP1 mutations occur in various malignancies, but malignancies arising from mutation of tumor suppressors have unexplained tissue proclivity." (PMID 34976173, 2022). "Regarding the somatic alteration of BAP-1, this appears in similar neoplasms in patients with a germline mutation." (PMID 36553016, 2022). "The high-risk group with worse prognosis possessed a higher frequency of BAP1 mutation, and a previous study has proved that BAP1 loss is associated with high tumor grade." (PMID 35651604, 2022). "The mutated frequency of BAP1 was also reported to be as high as 20% in ccRCC, with RCC accounting for 9% of BAP1 tumor predisposition syndrome (BAP1-TPDS)." (PMID 35425712, 2022). "The class 2 gene expression profile is strictly associated with classical factors of bad prognosis, such as larger tumor size, epithelioid cytology, extravascular looping matrix patterns, and monosomy 3 with BAP1 mutations." (PMID 35480119, 2022). "Of note, the genomic analysis of BAP1-related tumors has highlighted the loss of the remaining BAP1 wild-type allele, something that suggests the possible role as “two-hits” tumor suppressor gene by BAP1." (PMID 36013199, 2022). "BAP1 is one of several genes that is associated with epithelial-to-mesenchymal transition (EMT) of the tumor cells." (PMID 34775516, 2022). "Taken together, these findings provide a mechanistic link between BAP1 loss and the suppression of the tumor immune microenvironment in class 2 UMs, and they implicate the PROS1–MERTK pathway as a potential target for immunotherapy in UM." (PMID 35954340, 2022). "BAP1 inactivation status is strongly associated to high tumour grade and worse clinical outcomes in ccRCC patients." (PMID 36318367, 2022). "Typical radiologic features associated with BAP1 mutation include renal vein invasion, ill-defined tumor margins, and intratumor calcifications." (PMID 35565216, 2022). "BAP1 mutation has been associated with more aggressive disease and lower overall survival in ccRCC, with coagulative necrosis and high Furman grade on tumor pathology." (PMID 35565216, 2022).
tumor (continued). "One of the intriguing aspects of BAP1-deficient tumors is their variable prognosis depending on tumor type." (PMID 35381901, 2022). "Germline mutations in the BRCA-1 associated protein (BAP1) tumor suppressor gene underlie a tumor susceptibility syndrome characterized by increased risk uveal melanoma and melanocytic tumors (i.e., benign and malignant melanocyte-derived tumors)." (PMID 36077430, 2022). "Another tumor suppressor, BAP1, frequently found lost or mutated in cancers, has been shown to repress SLC7A11 expression thereby impairing cystine uptake and promoting ferroptosis in cancer cells." (PMID 35280777, 2022). "A tumor with a splicing mutation in BAP1 had also undergone loss of nBAP1, but had WT levels of cBAP1." (PMID 36077643, 2022). "To validate the functional role of the identified variants, we searched for BAP1 loss in the tumor tissues from the patients harboring mutations." (PMID 35885614, 2022). "Specifically, we sequenced germline DNA samples from 101 individuals with suspected BAP1-TPDS and validated pathogenic variants (PVs) by assessing BAP1 somatic loss in matching tumor specimens." (PMID 35885614, 2022). "This patient, along with BAP1 loss of heterozygosity in tumor cells (a frequent genetic event in iCCA), also carried a BAP1 germline mutation (c.255_255 + 6del)." (PMID 35755315, 2022). "In this study, we performed IHC on tumor samples from patient MPM_HO1901, detecting loss of BAP1 expression in different tumor types." (PMID 35885614, 2022). "We identified tumor-derived de novo UM mutations in 3/4 (75%) post-radiation AH samples in BAP1 or GNAQ." (PMID 35682905, 2022). "The majority (24/26) of tumor samples with likely pathogenic BAP1 mutations displayed loss of nBAP1." (PMID 36077643, 2022). "Mutations in BAP1 have been identified in a hereditary cancer predisposition syndrome and in sporadic tumours." (PMID 36318367, 2022). "BRCA1-associated protein 1 (BAP1) is a tumor suppressor gene with frequent inactivating mutations and deletions in human cancers." (PMID 35307036, 2022). "Additional driver mutations (SETD2, PBRM1, BAP1, and others) promote genomic instability and tumor cell metastasis through the dysregulation of various metabolic and immune-response pathways." (PMID 36428521, 2022). "BAP1 is a tumor suppressor gene that encodes a nuclear deubiquitinase, member of the ubiquitin C-terminal hydrolase family." (PMID 36362209, 2022). "Despite this varying tumor cell content and different tissues, hierarchical clustering using DMRs with a FC > 5 showed that UM metastases clustered together with either BAP1 or SF3B1-mutated UM implicating that they showed the same secondary driver signature." (PMID 34997020, 2022). "B cells play an important role in anti-tumor immunity; thus, the study concurs with previous ones that indicted that BAP1 mutations can have favorable effects on cancer progression." (PMID 36012262, 2022). "BAP1 was a critical tumor suppressor gene in ccRCC, prompting tumor development when mutated in the somatically." (PMID 35935986, 2022). "Given the relationship between loss of BAP1 expression and poor prognosis, it is important to clarify the impact of tumor size and age on the likelihood of a BAP1 mutation." (PMID 33903674, 2021). "BRCA1-Associated Protein 1 (BAP1) is a major tumor suppressor and belongs to the deubiquitinase superfamily." (PMID 34887768, 2021). "By contrast, Patient B’s tumor exhibited LOH across the entirety of chromosome 3 including the second BAP1 allele." (PMID 34504799, 2021). "Further, mutations in the BRCA1 associated protein-1 gene (BAP1), a tumor suppressor located on chromosome 3p, is mutated in 47% of all UM and a vast majority of metastasizing UM5,6." (PMID 33903674, 2021).
tumor (continued). "According to these functions, a tumor with a volume of 348 mm3 would have loss of BAP1 expression in 35 to 41% of its cells, or about 57 862 233 to 67 781 473 cells." (PMID 33903674, 2021). "Mutation of MLL3 results in the defect of BRCA1 associated protein 1 (BAP1) recruitment to the enhancers of tumor-suppressor genes, which represses enhancer activity and promotes tumorigenesis." (PMID 33824309, 2021). "BAP1 is encoded by 3p21 and is a tumour suppressor gene that encodes a nuclear deubiquitinase that regulates histone H2A to regulate transcriptional repression." (PMID 33741915, 2021). "In our study, we have alternately used loss of immunohistochemical expression of BAP1 in tumor cell nuclei and BAP1 mutations detected by DNA sequencing as a marker for the same genetic event, using methods replicated in our previous studies." (PMID 33903674, 2021). "In MM, tumor development is nevertheless characterized by a low mutation rate despite major structural chromosomal rearrangements driving oncogenesis (BAP1, NF2, CDKN2AB)." (PMID 34199066, 2021). "In conclusion, the BAP1 mutation occurs early in the growth of UM, well before the average tumor is diagnosed and the timing coincides with previous calculations of the tumor size at which seeding of micrometastases start." (PMID 33903674, 2021). "The tumor suppressor functions of BAP1 have been linked to its dual activity in the nucleus, where it has roles in DNA repair and transcription, and regulation of cell death and mitochondrial metabolism in the cytoplasm." (PMID 33805973, 2021). "In the patient without VHL mutation, we found alterations in CUL3, DOT1L, SETD2 and TSC1 in the primary tumor, with the addition of BAP1 gene mutation in its analyzable PMs." (PMID 34885018, 2021). "The mean number of cell doublings required to reach the number of tumor cells and number of tumor cells with BAP1 loss was 27.9 (SD 1.7, smallest tumor 24.2, largest tumor 30.7) and 25.8 (SD 3.2, smallest tumor 19.5, largest tumor 30.4), respectively." (PMID 33903674, 2021). "EIF1AX and SF3B1 mutations occur especially in low-risk D3 tumours, while BAP1 mutations are observed in most high-risk M3 UM." (PMID 34439175, 2021). "BAP1 is a tumor-suppressor gene located on chromosome 3; it encodes a deubiquitinating enzyme with tumor-suppressive activity." (PMID 33922591, 2021). "It has been well‐established that BAP1 is an important tumor suppressor and frequently mutated in many human cancers." (PMID 33155366, 2021). "A recent study also put in evidence that BAP1 mutations occur in the early steps of UM neoplastic development, before the tumour is even detected and with a timing that is likely to match the advent of the pioneer micrometastases." (PMID 35008260, 2021). "The molecular mechanisms underlying the tumor suppressor activities of BAP1 remain controversial, especially in the light of this and many other reports implicating BAP1 as a positive regulator of cell proliferation." (PMID 33912157, 2021). "Of the patients who had a solitary metastasis (n = 18), 11 had an aberrant BAP1 tumor and one with an SF3B1-mutated tumor." (PMID 34771480, 2021). "We confirmed that high levels of LAG3 expression in UM were positively associated with high-risk tumour parameters, such as epithelioid/mixed cell type and chromosome 3/BAP1 loss, and described an association with the presence of inflammatory cells." (PMID 34503258, 2021). "A loss of nuclear expression of ATM was observed in nearly 65% of the cases and it was significantly correlated with an epithelioid morphology of the UM cells, large tumour diameter above 10 mm, presence of TILs and nuclear BAP1 loss." (PMID 35008260, 2021).